CLIC1 (CLIC family member 1)
Diseases named in the same sentence as CLIC1 in open-access papers (continued):
Sharing a sentence is not in itself a finding about the gene and the disease.
tumor (continued). "Low CLIC1-expressing GSCs were able to generate 3D organoids, although showing a lower proliferating cell fraction, confirming that tumor formation may be, at least partially, independent from CLIC1 activity." (PMID 35135603, 2022). "CLIC1 expression in tumor cells stratified in ccRCC cases according to 4 classes." (PMID 36497464, 2022). "Inhibiting CLIC1 activity may reduce or prevent distant metastases by preventing tumor proliferation and migration, which contribute to distant metastases." (PMID 36727059, 2022). "CLIC1 is overexpressed in many tumor types and drives glioblastoma cell growth and proliferation." (PMID 33920158, 2021). "Consistent with previous research results, we observed that the expression of CLIC1, CLIC3, and CLIC5 was increased in cancer tissues; the expression of CLIC1 and CLIC3 was associated with the progression of the tumor; and a lower expression of CLIC1 was associated with better OS in HCC." (PMID 34766585, 2021). "It is postulated that CLIC1 has an important role in tumor development." (PMID 34785721, 2021). "CLIC1 was found to be expressed in the cytoplasm, membrane, and nucleus of tumor cells, indicating that it could play several biological functions depending on location." (PMID 33920158, 2021). "Metformin was able to block IAA-94-sensitive currents in tumor-derived stem cells but not normal stem cells, thus opening an exciting possibility that CLIC1 could be localized at the membranes only in tumor environments." (PMID 32116799, 2020). "CLIC4 is the other well studied CLIC member in tumor biology, along with CLIC1." (PMID 32116799, 2020). "It appears that the regulation of ROS levels by CLIC1 is tumor cell-type specific." (PMID 31316050, 2019). "The differential functional expression of CLIC1 between GSCs and their differentiated counterpart could represent a possible strategy to selectively recognize and hit the tumor stem cell subset." (PMID 30918838, 2019). "In this scenario, the peculiar ability of CLIC1 to change its functional localization depending on the activation state of the cells could be a compelling strategy to impair tumor cell proliferation and/or survival with a higher efficacy in CSCs." (PMID 30918838, 2019). "Results confirmed increased levels of CLIC1 coincident with CK20 in regions of the tumor." (PMID 29462791, 2018). "The CLIC1 expression levels of immunohistochemically stained samples were graded semi-quantitatively based on staining intensity and the percentage of positive tumor cells in the magnification ×100." (PMID 29796185, 2018). "Then the tumor tissues were identified by H&E staining and immunohistochemistry of CLIC1." (PMID 27825122, 2016). "CLIC1-knockdown can also slow down the tumor growth in vivo." (PMID 27825122, 2016). "However, further studies are required in order to clarify how CLIC1 protein contained in EVs contributes to tumor microenvironment remodeling." (PMID 26429879, 2015). "In vivo and in vitro proliferation of GBM CSCs depends on CLIC1 activity and its inhibition reduces tumor development in animal models, thus, CLIC1 could be a target for antiproliferative molecules." (PMID 25361004, 2014). "Thus, CLIC1 is hyperactivated in cancer cells which are in a highly proliferative state, and plays important roles in tumor invasion and metastasis." (PMID 22578365, 2012). "Interestingly, untransformed extracellular matrix (ECM) stiffness is involved in the complex regulation of metabolic reprogramming, including carbohydrate metabolism, with chloride intracellular channel 1 (CLIC1) acting as a bridge between tumor stromal stiffness and the Warburg effect in PDAC." (PMID 40630951, 2025). "In fact, some experimental evidence suggests that EXOs might enhance tumor cell resistance to anticancer agents, as they might up-regulate the expression of factors, for example, ion channels such as CLIC1, which are related to the reduced activity of anticancer agents such as VIN." (PMID 37242687, 2023).
tumor (continued). "In this context, the evidence that metformin inhibition of GSC proliferation and migration is dependent on the blockade of CLIC1-mediated ion currents, paved the way for the hypothesis that CLIC1 functional expression determines tumor cell sensitivity to metformin." (PMID 35135603, 2022). "In this context, CLIC1 could be predicted to regulate ROS generation in tumor cells." (PMID 32116799, 2020). "Importantly, differently from normal cells where only few channels are active, CLIC1 activity is increased in tumor cells, suggesting that CLIC1 could represent a tumor-specific drug target." (PMID 30186163, 2018). "Secreted CLIC1 protein may support tumor proliferation by (i) directly mediating the expansion of tumor cells, either bulk differentiated cells or CSCs, and (ii) molding tumor microenvironment." (PMID 26429879, 2015). "CLIC-1 is retained and overexpressed by cc-RCC tumor cells during malignant transformation, with its expression also observed on the stromal tumor blood vessel endothelium." (PMID 38746686, 2024). "For example, CLIC1 shows increased expression in cell lines and tissue samples from HPV+ CC patients and has been proposed as a tumor promoter." (PMID 37408210, 2023). "Tumor-derived EVs, EVs-c-Myc, KCNQ1OT1 or CLIC1 overexpression, or miR-556-3p inhibition promoted GC cell proliferative, invasive, and migrative capacities but repressed their apoptosis through activating PI3K/AKT pathway." (PMID 35260554, 2022). "Collectively, tumor-derived EVs carrying c-Myc activated KCNQ1OT1 to downregulate miR-556-3p, thus elevating CLIC1 expression to activate the PI3K/AKT pathway, which facilitated the growth and metastasis of GC." (PMID 35260554, 2022). "These proteins were initially identified as blood biomarkers of OC because human CLIC1 and CLIC4 were found into the blood of xenografted tumor-bearing mice and were significantly elevated in sera of EOC patients." (PMID 33562306, 2021). "We found that, in addition to interacting with CD2, CD58 was co-expressed and physically interacted with HOXB family genes (HOXB2, HOXB3, and HOXB5), AKAP12, CLIC1, CPNE3, etc., which were reported to be involved in tumor initiation and progression." (PMID 34193136, 2021). "The DNA methylation levels of the CLIC1–3 and CLIC5–6 promoters in tumor tissue with HCC were significantly lower in HCC tissues than in normal tissues." (PMID 34766585, 2021). "Several studies have reported CLIC1 to be an overexpressed protein in CRC, involved in cell migration and invasion, including more tumor recurrences and shorter patient survival, through the regulation of MMP-2 and MMP-9." (PMID 32353950, 2020). "Apart from WDR1, several other oncoproteins and tumour suppressors, such as LDHA, CLIC1, ARPC5, ZYX, RCN1, FHIT and CFTR, were identified in this study." (PMID 32601462, 2020). "Altogether, our data show that CLIC1 secreted by cancer cells via extracellular vesicles, modulates the activity of neighboring endothelial cells in a TRPM7 dependent manner, promoting tumor angiogenesis." (PMID 30279961, 2018). "CLIC1 and CLIC4 were initially identified as blood biomarkers of EOC because human CLIC1 and CLIC4 were shed into the blood of xenografted tumor-bearing mice and significantly elevated in sera of EOC patients." (PMID 30282979, 2018). "This is consistent with previous studies that identified the overexpression of CLIC1/CLIC4 in numerous cancer tissues including colon, prostate, pancreatic, and ovarian (26, –, 28), suggesting they directly contribute to tumor development." (PMID 29462791, 2018). "In this study, we evaluated CLIC1 and CLIC4 staining of EOC in tissue microarrays as well as fresh tumor tissue secretomes to complement our prior human serum biomarker studies." (PMID 30282979, 2018). "Across all malignant tumors, CLIC1 and CLIC4 stained 87% and 96% of the tumor cores, respectively, while CA125 stained only 75%." (PMID 30282979, 2018).
tumor (continued). "To evaluate the sensitivity of CLIC1 and CLIC4 staining for malignant tumor cores, we categorized the tumors based on their staining intensities and compared tumor subtypes." (PMID 30282979, 2018). "EVs derived from CLIC1-overexpressing GBM cells are strong inducers of proliferation in vitro and tumor engraftment in vivo." (PMID 26429879, 2015). "The proteomic clusters included tumor upregulated (PRDX3, APOA1, CLIC1) and downregulated (NFM, NDUS1, MDHC, ALDOC, STMN1, PEBP1, DDAH1, CN37) proteins." (PMID 25050814, 2014). "Researchers did not study the involvement of isolated CLIC1-positive stroma cells with endothelial morphology in the local initiation of tumor stroma vasculogenesis." (PMID 38746686, 2024). "CLIC1 expression in GBM cells is diffuse and uniform within tumor tissue." (PMID 35135603, 2022). "We propose that the identification of CLIC1-dependent tumors may allow the selection for GBM (and also other tumor types) patients likely receiving benefit from biguanide treatment." (PMID 35135603, 2022). "Furthermore, in vitro experiments demonstrated that CLIC1 and CLIC4 knockdown slowed the proliferation and migration of OC cells, indicating a potential role in tumor progression." (PMID 33562306, 2021). "Additionally, GB EVs induce tumor cell migration, invasion and proliferation by transferring L1CAM, annexin A2 and chloride intracellular channel-1 (CLIC1) to neighboring cells." (PMID 34210109, 2021). "Besides, a protein known as chloride intracellular channel-1 (CLIC1), found to be enriched in some TEVs, can be transferred via EVs into other recipient tumor cells and, thus, enhance tumor growth." (PMID 33628730, 2020). "In addition, both CLIC4 and CLIC1 are overexpressed in cancer stem cells and inhibition of CLIC4 expression inhibits tumor growth." (PMID 31879279, 2020). "Notably, the exosomes released by CLIC1-overexpressing GBM cells accelerate the in vitro cell proliferation and tumor engraftment in vivo." (PMID 33086616, 2020). "Chloride intracellular channel 1 (CLIC1) is a promising therapeutic target in cancer due to its intrinsic characteristics; it is overexpressed in specific tumor types and its localization changes from cytosolic to surface membrane depending on activities and cell cycle progression." (PMID 31316050, 2019). "CLIC1 staining of the malignant EOC tumors was observed only within the tumor nests but not in the adjacent stroma, whereas CLIC4 stained both tumor nests and surrounding stroma." (PMID 30282979, 2018). "In this study we evaluated the utility of CLIC1 and CLIC4 as EOC tissue biomarkers because we previously showed they are promising EOC serum biomarkers and have intriguing, but incompletely understood roles in EOC tumor progression." (PMID 30282979, 2018). "In contrast, the tumor nests in most EOC tumors were positive for CLIC1, while stromal cells were negative." (PMID 30282979, 2018). "Other studies have indicated that CLIC1 and CLIC4 may play roles in altering the EOC tumor microenvironment and affecting EOC tumor progression." (PMID 30282979, 2018). "CLIC1 protein has been found to be overexpressed in liver cancer tissues compared to noncancerous liver tissue and significantly correlated with tumor size, metastasis, and poor prognosis." (PMID 26881024, 2016). "Many reports suggest that CLIC1 and LGALS3BP locate in cell membrance and might promote the tumor progression of other cancers." (PMID 27825122, 2016). "Notably, EVs derived from CLIC1-overexpressing GBM cells accelerate cell growth in vitro and tumor engraftment in vivo." (PMID 26429879, 2015). "To assess whether the effect of CLIC1-containging EVs occurred also in vivo, we injected U87 MG cells with NT EVs, siCLIC1 EVs and CLIC1 FLAG EVs, or PBS as control, subcutaneously into one flank of nude mice and monitored tumor growth over time." (PMID 26429879, 2015).
tumor (continued). "Importantly, in vivo studies already demonstrated that CLIC1 is required for GBM tumorigenesis, and that metformin treatment of mice orthotopically xenografted with human GBM CSCs, reduced tumor growth, confirming the more copious in vitro results." (PMID 25361004, 2014). "Moreover, we identified four putative tumor-specific cryptic peptides from ZYG11A, RPL36A-HNRNPH2, CLIC1 and RPL31 that were decreasingly presented upon MAPKi in SK-Mel-28 wt but were unaffected in SK-Mel-28 dr cells, indicating a direct link to MAPK signaling." (PMID 39835134, 2024). "Acetylation stabilizes CLIC1, which is not ubiquitinated, leading to tumor development." (PMID 37048148, 2023). "As a result, our data illustrated that tumor-derived EVs could augment KCNQ1OT1 expression and reduce miR-556-3p expression by transferring c-Myc to GC cells to upregulate CLIC1 and activate the PI3K/AKT pathway, so as to enhance GC cell proliferating, migrating, and invasive potential." (PMID 35260554, 2022). "Conversely, this protein is less relevant for the survival/proliferation of normal stem cells (i.e. mesenchymal stem cells) and non-stem (differentiated) GBM cells composing the bulk of tumor, in which CLIC1 is mainly cytosolic and displays low activity as ion channel." (PMID 35135603, 2022). "Finally, the effects of CLIC1 and CLIC4 on tumor growth and migration suggest that they may be therapeutic targets and should be further investigated." (PMID 30282979, 2018). "However, the recent identification that CLIC1 activity is necessary for GSC proliferation, self-renewal and invasiveness, while it is dispensable for most non-transformed normal cell populations, opened new perspectives in the potential development of new therapeutics for this still incurable tumor." (PMID 30918838, 2019). "The three-marker panel of CLIC1, MAPRE1 and SERPINA3 exhibited significance regardless of tumor stage, grade, size, and menopausal status." (PMID 30963111, 2019). "As detailed in the previous paragraphs, CLIC1 behaves as CSC-specific target because, although expressed in most normal and differentiated (non-stem) tumor cells, it is mainly present as inactive cytosolic monomer, with a very low activation rate." (PMID 30918838, 2019). "CLIC1 and CLIC4 staining were not significantly affected by clinicopathological parameters such as age, race, disease stage, tumor grade, or tumor size." (PMID 30282979, 2018). "Three genes consisting of CLIC1, MAPRE1, and SERPINA3 in the refined TGFβ signature significantly stratified overall survival (log-rank p = 0.0141) in a larger validation cohort irrespective of menopausal status, tumor stage, grade, and size." (PMID 30963111, 2019). "Elevated CLIC4 expression, but not CLIC1 expression, was a negative indicator of patient survival, and CLIC4 knockdown in cultured cells decreased cell proliferation and migration indicating a potential role in tumor progression." (PMID 30282979, 2018). "Although the CLIC1 role in ccRCC has not been fully elucidated, several primary cell lines from ccRCC patients indicated that CLIC1 inhibition blocked the myosin light chain kinase (MYLK) and β3 integrin, decreasing tumor proliferation and slowing cancer progression." (PMID 33920158, 2021).
cancer (55 papers, 2010 to 2025). A tumor composed of atypical neoplastic, often pleomorphic cells that invade other tissues. "In a multitude of cancer types, CLIC1 has exhibited its potential as a diagnostic indicator and a therapeutic target." (PMID 38027011, 2023). "While being the most studied member of the CLIC family in the context of tumors, CLIC1 has the potential to be a diagnostic marker for several cancers as well as being a potential target for therapy." (PMID 32116799, 2020). "CLIC1 has been shown to be overexpressed in gaster cancer cells where it is associated with increased production of ROS in a hypoxia-reoxygenation induced state." (PMID 32116799, 2020). "The dependence on CLIC1/CLIC4 during MCPyV ST metastatic processes opens new insights into how viruses manipulate susceptible cells to mediate cancer progression." (PMID 29462791, 2018). "Additionally, CLIC1 was positively linked with cancer-immunity cycle, stromal activation, DNA damage repair and cell cycle." (PMID 38027011, 2023). "Literature reports CLIC1 to be linked to cancer development and neurodegenerative processes." (PMID 34357102, 2021). "CLIC1 plays critical roles in processes such as apoptosis, proliferation, invasiveness, and metastasis in cancer cells, but the underlying mechanisms remain unclear." (PMID 31316050, 2019). "For example, CLIC1 gene expression is significantly increased in bladder, in situ breast ductal and ovarian carcinomas, and it has been linked to oncogenic functions and poor prognosis in colorectal, gastric, hepatocellular, gallbladder, pancreatic, and lung carcinomas, and sarcomas." (PMID 30918838, 2019). "Therefore, the molecular mechanisms underlying cell migration and invasion in CLIC1-depleted ESCC cells appear to differ from those in other CLIC1-regulated cancer cells." (PMID 29796185, 2018). "Recent research indicates that CLIC1 plays a role in the advancement of cancer, yet the precise mechanism behind this phenomenon has yet to be fully elucidated." (PMID 40948771, 2025). "Targeting CLIC1 holds promise for malignant tumor treatment, although comprehensive mechanistic understanding and targeted therapies necessitate further research." (PMID 38027011, 2023). "In summary, CLIC1 plays a pivotal role in various cancer types, affecting proliferation, migration, invasion, and metastasis." (PMID 38027011, 2023). "CLIC1 presented positive interactions with all steps in the cancer immune cycle, proving the significance of CLIC1 in modulating anticancer immunity." (PMID 38027011, 2023). "High expression levels of CLIC1 and CLIC3 were associated with advanced cancer stage in HCC patients." (PMID 34766585, 2021). "CLIC1 expression in plasma membrane is strictly dependent on redox homeostasis and pH levels supporting tumorigenesis and development of cancer." (PMID 34357102, 2021). "The chloride intracellular channel 1 (CLIC1) is a chloride intracellular channel, and its expression is upregulated in many cancer cells." (PMID 34072894, 2021). "The differential expression pattern of CLIC4 and CLIC1 in distinct tissues and thus in cancer types suggests a variation in their functional roles." (PMID 31879279, 2020). "CLIC1 is not only important for cell cycle progression in cancer cells but also influences cell migration and metastatic invasion." (PMID 32116799, 2020). "Yet, our study supports the emerging potential of CLIC4 and CLIC1 as a therapeutic target in cancer progression." (PMID 31879279, 2020). "CLIC1 is the most widely expressed and studied channel of this family, in both physiological and pathological conditions, including brain functioning and cancer cell proliferation." (PMID 30918838, 2019). "CLIC1 displays several peculiar features which render this channel an ideal pharmacological target in cancer cells." (PMID 30918838, 2019).